CHST6 (carbohydrate sulfotransferase 6)
Description:
Sulfotransferase that utilizes 3'-phospho-5'-adenylyl sulfate (PAPS) as sulfonate donor to catalyze the transfer of sulfate to position 6 of non-reducing N-acetylglucosamine (GlcNAc) residues of keratan. Cooperates with B4GALT4 galactosyltransferase and B3GNT7 N-acetylglucosaminyltransferase to construct and elongate the sulfated disaccharide unit [->3Galbeta1->4(6-sulfoGlcNAcbeta)1->] within keratan sulfate polymer. Involved in biosynthesis of keratan sulfate in cornea, with an impact on proteoglycan fibril organization and corneal transparency. Involved in sulfation of endothelial mucins such as GLYCAM1.
Synonyms: C-GlcNAc6ST; hCGn6ST; GST4-beta; GlcNAc6ST-5; Gn6st-5; MCDC1
Tractability: Antibody: UniProt predicts a signal peptide or a membrane-spanning region.
Gene: Protein-coding gene on chromosome 16 (75,472,052 to 75,495,458, reverse strand). Ensembl gene ENSG00000183196.
Subcellular location: Golgi apparatus membrane
Pathways (Reactome):
Disease: Defective CHST6 causes MCDC1
Metabolism: Keratan sulfate biosynthesis
Gene Ontology:
Molecular function: keratan sulfotransferase activity; N-acetylglucosamine 6-O-sulfotransferase activity; sulfotransferase activity
Biological process: keratan sulfate proteoglycan biosynthetic process; N-acetylglucosamine metabolic process; sulfur compound metabolic process; carbohydrate metabolic process
Cellular component: Golgi apparatus; Golgi membrane; trans-Golgi network
Genetic constraint (gnomAD): Loss-of-function variants: 1 observed, 2.15 expected, observed/expected ratio (o/e) 0.47, 90% interval 0.16 to 1.71. That is too few expected variants to judge how well the gene tolerates losing a copy. Missense variants: 698 observed, 589.21 expected, observed/expected ratio (o/e) 1.18, 90% interval 1.11 to 1.26. Synonymous variants: 309 observed, 271.15 expected, observed/expected ratio (o/e) 1.14, 90% interval 1.04 to 1.25.
Gene-disease validity (ClinGen):
ClinGen rates the evidence that CHST6 causes each of these diseases.
macular corneal dystrophy (autosomal recessive): Definitive. Macular corneal dystrophy (MCD) is a rare, severe form of stromal corneal dystrophy characterized by bilateral ill-defined cloudy regions within a hazy stroma, and eventually severe visual impairment.
Homologues: Orthologues: chimpanzee CHST6 (99% identical), macaque CHST6 (97% identical), Drosophila melanogaster CG31637 (23% identical), Drosophila melanogaster CG9550 (16% identical). Paralogues in human: CHST5 (84% identical), CHST4 (52% identical), CHST2 (36% identical), CHST7 (36% identical), CHST1 (33% identical), CHST3 (32% identical).
Diseases named in the same sentence as CHST6 in open-access papers:
CHST6 is named in the same sentence as 39 diseases in open-access papers, as found by Europe PMC text mining. Sharing a sentence is not in itself a finding about the gene and the disease. The quoted sentences say what the papers report.
macular corneal dystrophy (19 papers, 2009 to 2025). "The sulfotransferase CHST6 plays an important role in keratan sulfonation, and mutations in the corresponding gene cause macular corneal dystrophy." (PMID 35732154, 2022). "Macular corneal dystrophy (MCD) is ascribed to mutations in the carbohydrate sulfotransferase (CHST6) gene affecting keratan sulfate (KS) hydrophilicity and causing non-sulfated KS to precipitate in keratocytes and the corneal stroma." (PMID 32983576, 2020). "To date, over 130 mutations have been reported in the CHST6 gene and linked to macular corneal dystrophy." (PMID 32903857, 2020). "In view of the different clinical presentation seen in the mother, who resembled macular corneal dystrophy, the affected family members were screened for mutations in the CHST6 gene, which are known to cause macular corneal dystrophy." (PMID 21203343, 2010). "CHST6, a carbohydrate sulfotransferase-encoding gene, is associated with macular corneal dystrophy and may function as a prognostic indicator for low-grade gliomas." (PMID 40108724, 2025). "Macular corneal dystrophy (MCD) is an autosomal recessive disorder mainly caused by gene mutations of carbohydrate sulfotransferase (CHST6) leading to bilateral visual impairment." (PMID 29221207, 2017). "Gene mutation analysis of CHST3, CHST6 and CHST14 should be performed whenever there is suspicion of spondyloepiphyseal dysplasia, Ehlers-Danlos syndrome, macular corneal dystrophy and ARMJD, respectively." (PMID 37545696, 2023). "Macular corneal dystrophy has mostly been correlated with mutations in the carbohydrate sulfotransferase 6 (CHST6) gene, which encodes the enzyme carbohydrate sulfotransferase 6, which catalyzes the transfer of a sulfate group to the GlcNAc residue of KS." (PMID 32903857, 2020). "Interestingly, macular corneal dystrophy (MCD), a noninflammatory clouding of the cornea, has been linked to mutations in the carbohydrate sulfotransferase 6 gene (CHST6) involved in the biosynthesis of sulfated KS." (PMID 34071909, 2021).
corneal dystrophy (6 papers, 2009 to 2021). The term corneal dystrophy embraces a heterogeneous group of bilateral genetically determined non-inflammatory corneal diseases that are usually restricted to the cornea. "Individuals with CHST6 variants might experience similar corneal dystrophy symptoms, but the underlying mechanisms for their diseases might be different at the molecular level." (PMID 30716718, 2019). "Allelic heterogeneity is a typical feature of CHST6-related corneal dystrophy, which occurs when tens or even hundreds of different alleles within the same gene cause similar phenotypes." (PMID 33816482, 2021). "This suggests that in contrast to TGFBI (transforming growth factor, beta induced) with its hot spots for corneal dystrophy-associated amino acid substitution, CHST6 does not demonstrate a highly conserved number of disease-causing mutations." (PMID 19223992, 2009).
adenomyosis (1 paper, 2025). The growth of endometrial tissue inside the muscular wall of the uterine corpus. "At the molecular level, several enzymes involved in keratan sulfate biosynthesis were consistently upregulated in eutopic endometrium from adenomyosis patients, including B4GALT1, B3GNT2, CHST1, and CHST6." (PMID 41356013, 2025).
Burkitt lymphoma (1 paper, 2019). A rare form of malignant mature B-cell non-Hodgkin lymphoma. "For example, repression of CHST6 increased radiation-induced apoptosis of human Burkitt’s lymphoma cells, and more relevantly, CHST6 deficiencies were found to trigger ER stress with considerable GRP78/CHOP upregulation and cell apoptosis in MCD keratocytes." (PMID 30716718, 2019).
corneal diseases (1 paper, 2019). "We also found association of variants at known disease loci, TCF4 and CHST6 (FCED and MCD, respectively), with cell density and HEX, demonstrating how these structural measurements are affected by corneal diseases." (PMID 30894546, 2019).
Headache (1 paper, 2022). Cephalgia, or pain sensed in various parts of the head, not confined to the area of distribution of any nerve. "Cross-trait gene-based overlap analysis identified 33 genes significantly associated (Pgene-based < 3.85 × 10−6) with migraine and T2D, and 11 genes associated with headache and T2D, with 7 genes (EHMT2, SLC44A4, PLEKHA1, CFDP1, TMEM170A, CHST6, and BCAR1) common between them." (PMID 36292730, 2022). "Notably, seven of these genes (EHMT2, SLC44A4, PLEKHA1, CFDP1, TMEM170A, CHST6, and BCAR1) were genome-wide significant for all three traits (migraine, headache, and T2D)." (PMID 36292730, 2022).
lung adenocarcinoma (1 paper, 2025). A carcinoma that arises from the lung and is characterized by the presence of malignant glandular epithelial cells. "To extend beyond A549 cells, we performed CHST6 knockdown experiments in the PC-9 lung adenocarcinoma cell line." (PMID 41415903, 2025).
lung carcinoma (1 paper, 2025). "Further functional validation confirmed that CHST6 promotes lung cancer cell proliferation, migration, and invasion, suggesting its functional relevance in tumor biology." (PMID 41415903, 2025). "Functional validation confirmed that CHST6 promotes lung cancer cell proliferation, migration, and invasion." (PMID 41415903, 2025). "Scratch wound healing assays demonstrated that CHST6 enhances the migratory capacity of lung cancer cells (p < 0.01 for A549 cells)." (PMID 41415903, 2025).
nodular goiter (1 paper, 2021). Goiter characterized by discrete tissue mass(es) that may or may not produce thyroid hormones. "CHST6, FBP2, PPFIA4, and TGFBI proteins were all upregulated in THCA tissues compared with nodular goiter tissues." (PMID 33981593, 2021).
cancer (3 papers, 2020 to 2025). A tumor composed of atypical neoplastic, often pleomorphic cells that invade other tissues. "CHST6 has been shown to play a role in cell adhesion and migration, which are crucial processes in cancer metastasis." (PMID 40149981, 2025). "The duplication encompasses 6 genes four of which are frequently deregulated in cancer (TMEM170A, CHST6, CHST5, TMEM231)." (PMID 35221838, 2022). "Relative PAM, STC1, and HDAC4 expression were down-regulated, whereas CASP6, CHST6, SLC16A3, TPI1, KDELR3, VCAN, and CLDN9 were highly expressed in carcinoma tissues compared to the para-carcinoma tissues." (PMID 33424916, 2020).
tumor (3 papers, 2019 to 2025). "Compared with normal kidney tissues, antibody stainings for ANKZF1, CD44, IDUA, KIF20A, PLOD2, and VCAN were high in ccRCC tumor tissues, whereas they were low for CHST6, HS6ST2, NDST3 and FBP1." (PMID 33836688, 2021). "The results showed that CLDN9, AK4, PC, GPC1, and SRD5A3 were upregulated in EC tissues compared to in normal endometrium tissues, whereas B4GALT1, GMPPB, B4GALT4, and CHST6 were downregulated in tumor tissues." (PMID 31807118, 2019).
genetic disease (1 paper, 2021). "The defects in CHST6 can cause MCD (OMIM 217800), an autosomal recessive genetic disease characterized by bilateral progressive stromal opacity and loss of vision, which ultimately requires corneal transplantation." (PMID 33816482, 2021).
CHST6 also shares sentences with these, for which no sentence is quoted: gelatinous drop-like corneal dystrophy (2 papers); amyotrophic lateral sclerosis (1); autosomal recessive inherited disorder (1); chronic lung disease (1); chronic obstructive pulmonary disease (1); congenital stromal corneal dystrophy (1); connective tissue diseases (1); cystic fibrosis (1); Ehlers-Danlos syndrome (1); Ehlers-Danlos syndrome musculocontractural type 1 (1); fleck corneal dystrophy (1); Fuchs endothelial corneal dystrophy (1); gastric cancer (1); glioma (1); Granular corneal dystrophy (1); idiopathic pulmonary fibrosis (1); lattice corneal dystrophy (1); migraine (1); myopia (1); neurological disorders (1); pancreatic cancer (1); Peters plus syndrome (1); posterior polymorphous corneal dystrophy (1); Schnyder corneal dystrophy (1); spondyloepiphyseal dysplasia (1); stromal dystrophies (1); uveal melanoma (1).